NLRP3 (NLR family pyrin domain containing 3)
Diseases named in the same sentence as NLRP3 in open-access papers (continued):
Sharing a sentence is not in itself a finding about the gene and the disease.
ZIKV infection (17 papers, 2017 to 2025). "Thus ZIKV NS5 as an activator of the NLRP3 inflammasome plays important roles in ZIKV infection and associated diseases." (PMID 29317641, 2018). "However, whether NLRP3 inflammasome participates in the kidney injury induced by ZIKV infection and its underlying mechanism remain unknown." (PMID 31474993, 2019). "Immunoblot analysis further confirmed that ZIKV infection significantly decreased the expression levels of NLRP3-EGFP (FLAG-tagged)." (PMID 39976465, 2025). "In summary, we identified that ZIKV infection inhibits the expression of both NLRP3 and A20 at the protein level, thereby impairing cell death." (PMID 39976465, 2025). "To investigate how ZIKV infection impairs NLRP3 inflammasome activation, we reconstituted NLRP3-EGFP in the HeLa cell line following established protocols." (PMID 39976465, 2025). "To explore the mechanism by which ZIKV infection regulates pyroptosis, we reconstituted the NLRP3-EGFP construct in the HeLa cell line." (PMID 39976465, 2025). "In this study, we demonstrate that ZIKV infection significantly reduces the expression of NLRP3 and A20 proteins through post-transcriptional or translational processes, which leads to inhibited cell death." (PMID 39976465, 2025). "In conclusion, our study demonstrates that ZIKV infection impedes cell death by downregulating the expression of NLRP3 and A20." (PMID 39976465, 2025). "In this study, we uncover that RIG-I, a cytoplasmic dsRNA sensor, can recruit caspase-8, RIPK1, ASC, caspase-1, and NLRP3, forming a more complex PANoptosome to activate PANoptosis following ZIKV infection." (PMID 41263557, 2025). "Our results revealed significant reductions in the protein expression levels of NLRP3 and A20, attributable to post-transcriptional or translational effects during ZIKV infection." (PMID 39976465, 2025). "ZIKV infection causes severe inflammation through NOD-, LRR-, and pyrin domain-containing protein 3 (NLRP3) inflammasome-mediated IL-1β production." (PMID 36831177, 2023). "Cells or mice deficient in NLRP3 exhibited a decreased secretion of IL-1β and increased type I IFN production following ZIKV infection, as well as increased host resistance to ZIKV-induced effects in vivo and in vitro." (PMID 36831177, 2023). "Conversely, in vitro and in vivo NLRP3 deficiency upregulated type-I IFN and strengthened the host’s resistance to ZIKV, confirming NLRP3’s role in ZIKV infection." (PMID 37189617, 2023). "It was reported that NLRP3 inflammasome activation, triggered by ZIKV infection in monocytes, promotes the cleavage of cGAS, resulting in the inhibition of initiating type I IFN signaling, and enhances viral replication." (PMID 35446851, 2022). "Several studies have shown that ZIKV infection can activate the NLRP3 inflammasome, which results in the secretion of pro-inflammatory cytokines." (PMID 35446851, 2022). "ZIKV infection also induces the expression of inflammasome marker NOD-like receptor protein 3 (NLRP3), which prevents the interferon type 1 (IFN-1) antiviral response." (PMID 35632746, 2022). "Previous studies have shown that ZIKV infection activates the NLRP3 inflammasome, which leads to processing of pro-caspase-1 and secretion of IL-1β in infected monocytic cell lines, PBMC, or monocyte-derived macrophages." (PMID 35446851, 2022). "Several recent studies demonstrate that ZIKV infection activates or inhibits NLRP3 inflammasome and pyroptosis." (PMID 36016430, 2022). "The pyroptosis in human and murine macrophages was dependent on the NLRP3 inflammasome activation induced by ZIKV infection." (PMID 35446851, 2022). "ZIKV infection activated NLRP3 inflammasome in HK-2 cells, which indicated by the increased expression level of NLRP3, ASC, cleaved-caspase-1, pro-IL-1β and mature IL-1β." (PMID 31474993, 2019).
ZIKV infection (continued). "More importantly, inhibition of the NLRP3 inflammasome alleviated ZIKV infection-induced kidney injury, which was indicated by the decreased expression of AKI-related biomarkers in the mouse kidneys." (PMID 31474993, 2019). "Overall, we concluded that ZIKV infection induced AKI by triggering NLRP3 inflammasome activation and inflammatory response in the kidneys." (PMID 31474993, 2019). "ZIKV infection suppressed Bcl-2 expression and induced excessive inflammatory responses by activating the NLRP3 inflammasome, which subsequently led to kidney injury shown by impaired glomerular filtration and tubular re-absorption ability." (PMID 31474993, 2019). "In summary, our findings illustrated the mechanism of ZIKV infection induced AKI through activating NLRP3 inflammasome via suppressing Bcl-2." (PMID 31474993, 2019). "Overall, our findings demonstrated that ZIKV infection induced AKI by activating NLRP3 inflammasome and apoptosis through suppressing Bcl-2 expression, which provided potential therapeutic targets for ZIKV-associated renal diseases." (PMID 31474993, 2019). "ZIKV infection activated NLRP3 inflammasome and triggered the production of IL-1β in the kidney, which directly decreased the expression of aquaporins, thus leading to the water re-absorption disorder." (PMID 31474993, 2019). "ZIKV infection triggered the inflammatory response and renal cell injury by activating Nod-like receptor 3 (NLRP3) inflammasome and secreting interleukin-1β (IL-1β)." (PMID 31474993, 2019). "In this study, a novel mechanism by which ZIKV infection activates the NLRP3 inflammasome to facilitate IL-1β maturation is revealed." (PMID 29317641, 2018). "Here we reveal a mechanism by which ZIKV infection induces host inflammatory responses by facilitating the NLRP3 inflammasome assembly and IL-1β secretion." (PMID 29317641, 2018). "Our data proposes a novel approach for the treatment of ZIKV infection by inhibiting inflammasome, NLRP3 protein." (PMID 29167459, 2017). "Our data showed that ZIKV infection activates NLRP3 while inhibiting IFNα production in the monocytes." (PMID 29167459, 2017). "Consequently, we investigated the regulatory mechanism of the NLRP3 inflammasome and apoptosis in the context of ZIKV infection." (PMID 39976465, 2025). "Given that autophagy and proteasome pathways are known to regulate NLRP3 expression (36, –, 38), we investigated whether these pathways are necessary for the decrease in NLRP3 expression observed following ZIKV infection." (PMID 39976465, 2025). "Moreover, we noted a significant decrease in Ni-induced puncta formation in ZIKV-infected cells, indicating that ZIKV infection downregulates NLRP3 expression, thereby impairing both NLRP3 puncta formation and inflammasome activation." (PMID 39976465, 2025). "Given the key role of NLRP3 inflammasome in innate immune responses by activating caspase-1 to promote IL-1β secretion and pyroptosis, we examined whether ZIKV infection stimulates IL-1β secretion through NLRP3 inflammasome activation in THP-1 cells." (PMID 37191498, 2023). "Thus, ZIKV infection of THP-1 cells activates the NLRP3 inflammasome and consequently induces IL-1β maturation and secretion." (PMID 37191498, 2023). "Serum samples from pregnant (n = 18) and non-pregnant (n = 22) women with acute ZIKV infection were assessed for NLRP3, IL-1β, IL-18, and GDF3 markers through an enzyme-linked immunosorbent assay." (PMID 35632746, 2022). "This may indicate that ZIKV infection can trigger Golgi fragmentation in macrophages derived from the monocytic U937 cell line, but most probably independently of NLRP3." (PMID 33208442, 2021). "In our study, the inhibition of NLRP3 inflammasome activation slightly suppressed ZIKV infection-induced cell death, indicating that NLRP3 inflammasome activation contributed to cell death, but it was not enough to eliminate the ZIKV infection-induced cell death." (PMID 31474993, 2019).
ZIKV infection (continued). "Since Bcl-2 attenuated the activation of NLRP3 inflammasome and apoptosis of renal cells, we further confirm whether Bcl-2 reduced renal cell injury induced by ZIKV infection." (PMID 31474993, 2019). "Therefore, our work identified a novel role of ZIKV infection in inducing AKI by activating NLRP3 inflammasome via suppressing Bcl-2." (PMID 31474993, 2019). "Even though the role of Bcl-2 in NLRP1 inflammasome activation mechanism is well-appreciated, it's still unknown whether Bcl-2 is involved in regulating NLRP3 inflammasome activation induced by ZIKV infection." (PMID 31474993, 2019). "Thus we demonstrate that ZIKV infection triggers IL-1β secretion by activating the NLRP3 inflammasome." (PMID 29317641, 2018). "Thus we reveal that ZIKV infection and protein production are required for the NLRP3 inflammasome activation." (PMID 29317641, 2018). "However, activating NLRP3 inflammasome in macrophages during ZIKV infection remains controversial." (PMID 39976465, 2025). "However, the mechanism by which host cells induce or inhibit NLRP3 activation during ZIKV infection remains unclear (22, –, 25)." (PMID 39976465, 2025). "Consequently, we determined whether caspase-1 and GSDMD cleavage resulting from activation of the NLRP3 inflammasome were induced by ZIKV infection." (PMID 37191498, 2023). "In our investigation, we observed an upregulation of NLRP3 expression in ZIKV-infected iBMDMs, indicating that ZIKV infection activates the NF-κB signaling pathway." (PMID 39976465, 2025). "We further elucidated that ZIKV infection drives PANoptosome formation, with RIG-I nucleating the complex by recruiting ASC, caspase-1, NLRP3, caspase-8, and RIPK1 to activate PANoptosis." (PMID 41263557, 2025). "The results showed that acute ZIKV infection induces more intensive GDF3, NLRP3, IL-1β, and IL-18 expression in the context of pregnancy." (PMID 35632746, 2022). "In conclusion, this study demonstrated that acute ZIKV infection during pregnancy triggers overexpression of the growth factor GDF3 and the inflammasome-related factors NLRP3, IL-1β, and IL-18." (PMID 35632746, 2022). "We observed a strong induction of Golgi fragmentation induced by ZIKV infection in WT Huh7 cells, but this increase was found to be independent of NLRP3." (PMID 33208442, 2021). "More importantly, Bcl-2 played a negative role in both ZIKV infection-induced NLRP3 inflammasome activation and apoptosis by down-regulating the NLRP3 priming and the expression of pro-apoptotic proteins, respectively." (PMID 31474993, 2019). "IL-1β mRNA expression and protein secretion were activated by ZIKV but not by inactivated ZIKV, indicating that ZIKV infection is required for the NLRP3 inflammasome activation." (PMID 29317641, 2018). "In contrast, we observed that, while ZIKV infection could trigger Golgi fragmentation in macrophages derived from both monocytic U937 cells and Huh7 cells, this was NLRP3 independent, unlike HCV." (PMID 33208442, 2021). "In our study, NLRP3 inflammasome could be activated by ZIKV infection in non-immunocytes renal epithelia cells HK-2." (PMID 31474993, 2019). "Taken together, we reveal that ZIKV infection and protein production, but not ZIKV genomic RNA, are required for the activation of NLRP3 inflammasome." (PMID 29317641, 2018). "Since NLRP3 depletion does not prevent the Golgi fragmentation induced by ZIKV in either of the cell lines used, this implies that other mechanisms/pathways can be in play in the context of ZIKV infection." (PMID 33208442, 2021).
corneal infection (16 papers, 2013 to 2025). A viral or bacterial infectious process affecting the cornea. "A prior study in mice showed that HSV-1 causes more severe keratitis after corneal infection in NLRP3 KO mice compared to WT." (PMID 32101570, 2020). "Considering that neutrophils are the primary source of IL-1β during MRSA corneal infections, we investigated if α-hemolysin induces neutrophil IL-1β secretion under defined in vitro conditions and if this is dependent on the canonical NLRP3 pathway." (PMID 41415470, 2025). "These outcomes show that the GSDMD and NLRP3 protein expressions play an important role in S. pseudintermedius-mediated corneal ulceration." (PMID 38515339, 2024). "An mRNA analysis of 110 patients with corneal ulcers showed heightened expression of NOD-like receptor protein 3 (NLRP3) and increased levels of inflammatory cytokines such as interleukin-1β (IL-1β), IL-8, and IL-17." (PMID 38533385, 2024). "Consistent with these in vitro findings, we identified a selective role for NLRP3 in regulating P. aeruginosa growth and disease severity in a murine model of blinding corneal infection." (PMID 37730693, 2023). "In an S. pneumoniae corneal infection model, NLRP3-dependent IL-1β secretion by neutrophils controlled their own recruitment to facilitate bacterial clearance at the expense of increased keratitis." (PMID 35406754, 2022). "In a model of the ocular herpes stromal keratitis, NLRP3-/- mice demonstrated a more robust early immune response, suggesting that NLRP3 plays an immunomodulatory role in corneal infection." (PMID 33524073, 2021). "Prior studies found that corneal infection of NLRP3-/- mice results in more severe immunopathogenesis, and that corneal HSV-1 infection induces the NLRP3, NLRP12, and IFI16 inflammasomes." (PMID 33524073, 2021). "However, Nlrp3–/– mice have worse pathology after corneal infection." (PMID 36146839, 2022). "Since induction of inflammasomes triggers Caspase-1 activation, we next determined whether corneal infection with virulent HSV-1 strains would enhance the expression levels of one or several of the five major inflammasomes: NLRP3, NLRP6, NLRP12, IFI16/p204, and AIM2." (PMID 31367214, 2019). "In addition, it has been shown that ASC inflammasomes, including AIM2 and NLRP3 activate caspase-1 in pneumococcal infection and especially, pneumolysin, a major virulence factor of S. pneumoniae, activate NLRP3/ASC inflammasome in a murine model of S. pneumoniae corneal infection." (PMID 26683708, 2015). "We found that neutrophils comprised >90% cells in corneal ulcers, and that there was elevated expression of TLR2, TLR4, TLR5 and TLR9, the NLRP3 and NLRC4 inflammasomes and the ASC adaptor molecule." (PMID 23750216, 2013). "Additionally, during S. pneumoniae corneal infection, the extracellular release of ATP also induced K+ efflux in P2X receptor 7 (P2X7R)-expressing neutrophils, culminating in NLRP3 inflammasome oligomerization." (PMID 35406754, 2022).
knee osteoarthritis (16 papers, 2016 to 2026). "Our last study also revealed the vital role of NLRP3 inflammasome, highly associated with tissue hypoxia, in the onset and development of knee osteoarthritis (KOA)." (PMID 33814979, 2021). "Notably, ACSL1, which is related with PPAR signaling pathway has been demonstrated to be closely associated with knee osteoarthritis and NLRP3." (PMID 40790756, 2025). "According to our findings, moxibustion promotes autophagic flux and lysosomal degradation of NLRP3, relieving knee osteoarthritis pain and swelling." (PMID 40790756, 2025). "The function of NLRP3 inflammasome has been reported in the pathogenesis of many arthritic diseases, such as gout, knee osteoarthritis, and rheumatic arthritis." (PMID 36466156, 2022). "NLRP3 inflammasome-mediated synoviocyte pyroptosis was reported to be involved in the progress of knee osteoarthritis." (PMID 36466156, 2022). "In a mouse model of knee osteoarthritis, extracellular vesicles inhibited the downregulation of NLRP3 expression activity via modification of NLRP3 mRNA by METTL3-m6A in macrophages and inhibited the secretion of IL-1β and IL-18 inflammatory factors and inflammatory responses." (PMID 39108751, 2024). "NLRP-3 inflammasome and NLRP-1 inflammasome induced pyroptosis in human primary fibroblast-like synoviocytes (FLS) collected from knee osteoarthritis patients under the stimulation of LPS/ATP." (PMID 38235147, 2023). "In rats with knee osteoarthritis, chrysin can alleviate neuropathic pain and reduce peripheral sensitization by inhibiting both the HMGB1-mediated activation of the RAGE/PI3K/AKT pathway and the NLRP3 inflammasome, leading to a reduction in synovitis." (PMID 40333577, 2025).
lipid metabolism disorders (16 papers, 2012 to 2025). "Recently, the Dixit VD team found that the release of NLRP3 inflammasomes in adipose tissue macrophages causes lipid metabolism disorders through catechol degradation." (PMID 36330745, 2022). "HG could cause lipid metabolism disorder, and NLRP3 inflammasome participated in lipid metabolism process 70, so whether H2S could improve lipid metabolism through NLRP3 inflammasome to alleviate DCM needed further study." (PMID 33110394, 2020). "In NAFLD, activation of the NLRP3 inflammasome is considered an important driver of liver inflammation and lipid metabolism disorders." (PMID 39850131, 2024). "The metabolite lactic acid produced by bifidobacteria alleviates inflammation and lipid metabolism disorders in NAFLD mice induced by a HFD through the inhibition of the NLRP3 inflammasome activation." (PMID 39850131, 2024). "Lactic acid can alleviate lipid metabolism disorders in NAFLD induced by diet through the inhibition of inflammation mediated by the NLRP3 inflammasome and the regulation of the autophagy process." (PMID 39850131, 2024). "We found that fgl2 interacted with TLR4 on macrophages and regulated inflammatory signaling pathways and the Nod-like receptor protein 3 (NLRP3) inflammasome, leading to liver damage and lipid metabolism disorders in the progression of NASH." (PMID 32863955, 2020). "The data presented herein are related to the research article entitled “Magnesium isoglycyrrhizinate blocks fructose-induced hepatic NF-κB/NLRP3 inflammasome activation and lipid metabolism disorder”." (PMID 29896493, 2018). "The findings indicate that lactic acid may alleviate lipid metabolic disorders through the suppression of NLRP3 inflammasome activation and inhibition of autophagy, while NLRP3 overexpression reverses these protective effects of lactic acid." (PMID 39850131, 2024). "In NAFLD, excessive NLRP3 activation not only triggers hepatic inflammation but may also inhibit autophagy, aggravating lipid metabolism disorders." (PMID 39850131, 2024). "In conclusion, this study reveals the significant role of bifidobacteria and its metabolite lactic acid in improving NAFLD, particularly through the inhibition of the NLRP3 inflammasome and modulation of autophagy to alleviate liver inflammation and lipid metabolism disorders." (PMID 39850131, 2024). "Importantly, lactic acid has been shown to inhibit NLRP3 inflammasome activation, suggesting its potential role in alleviating both inflammation and lipid metabolism disorders in NAFLD." (PMID 39850131, 2024). "In our study, TGQZD might promote the formation of CGI-58 and inhibit the expression of NLRP3 inflammasome, which can effectively improve the lipid metabolism disorder and inflammatory injury of hepatocytes induced by HFD." (PMID 35586044, 2022). "OxLDL and cholesterol crystals can activate NLRP3 inflammasome, and thereby the NLRP3 inflammasome may be a key intermediate link in the induction of inflammation by lipid metabolism disorders." (PMID 34163481, 2021). "Excessive NLRP3 activation initiates the transcription and translation of downstream inflammatory cytokines, and a large number of inflammatory factors contribute to the progression of lipid metabolic disorders, accelerating the development of NAFLD." (PMID 31841118, 2019). "In this review, we focus on the mechanisms by which AS-IV improves DKD by regulating NLRP3 inflammasome activation, including anti-inflammatory, antioxidative stress, reducing endoplasmic reticulum stress (ERS), regulating lipid metabolism disorders, and reducing pyroptosis." (PMID 41362412, 2025).